TIGIT (T cell immunoreceptor with Ig and ITIM domains)
Diseases named in the same sentence as TIGIT in open-access papers (continued):
Sharing a sentence is not in itself a finding about the gene and the disease.
tumor (continued). "Particularly, TIGIT plays a role in regulating antitumor immunity mediated by tumor-infiltrating microorganisms." (PMID 35037899, 2022). "TIGIT expression was observed in immune cells from the tumor microenvironment, whereas PVR was mainly expressed by tumor cells." (PMID 36544779, 2022). "T cell inhibitory receptors, such as CTLA-4, PD-1, and TIGIT, are essential for limiting immunopathology and terminating effective immune responses, but also can restrain effective anti-tumor immune responses." (PMID 35263569, 2022). "We also found DC-STAMP expression had a correlation with PDCD1, CD274, CTLA-4, and TIGIT which were exhaustion markers of T cells and considered a dysfunction of anti-tumor immunity." (PMID 35571050, 2022). "Patients with T2 tumors were more likely to have increased expression of PD-1, LAG-3, and TIGIT on tumor-infiltrating CD8+ cytotoxic T cells than those with T1 tumors." (PMID 36271406, 2022). "Following TIGIT blockade in MM-bearing mice, tumor burden was significantly reduced, and survival was prolonged in a CD8+ T cell-dependent manner." (PMID 35327475, 2022). "Remarkably, TIGIT inhibition, both alone and in combination with PD-1 inhibition, mainly acts on NK cells to increase the anti-tumor activity of CD8+ T cells." (PMID 36231109, 2022). "In particular, the anti-tumor activity of a combination of anti-PD-L1 and anti-TIGIT mAbs has been shown to be abolished by CD226 blockade." (PMID 36428727, 2022). "TIGIT is an immune checkpoint receptor expressed on the surface of Treg cells, cytotoxic T cells and NK cells, as well as tumor-infiltrating T cells." (PMID 35572593, 2022). "In recent years, the T cell immunoglobulin and ITIM domain (TIGIT) immune receptor has garnered interest for its role in tumor immunosurveillance." (PMID 35327475, 2022). "The combination of SEA-TGT and anti-PD-1 depletes T cells with high expression of TIGIT and reverses T cells exhaustion, thereby enhancing anti-tumor immunity." (PMID 36558902, 2022). "T cell suppressor receptors such as CTLA-4, PD-1, and TIGIT are essential for T cell activation, antigen recognition, and recruitment, and can inhibit effective anti-tumor immune responses." (PMID 36703779, 2022). "Other ICBs combined with TIGIT blocking can enhance the anti-tumor immune response, such that blocking TIGIT and PD-1 together can enhance the proliferation of CD8+ T cells and protect memory T cells." (PMID 35590394, 2022). "To further analyze the significance of the findings here in human tumors, we investigated APOE, PD-1 and TIGIT protein expressions from 30 human tumor specimens by using immunohistochemistry." (PMID 36147474, 2022). "More importantly, the expression of PVR/TIGIT appears to be essential for the suppressive activity of Tregs in the tumor microenvironment." (PMID 36552960, 2022). "We also compared TIGIT expression in T cells isolated from human PDAC (n = 10) and a limited number (n = 2) of adjacent uninvolved tissue and noted a significantly higher TIGIT expression in tumor tissues than in uninvolved adjacent tissues." (PMID 36569934, 2022). "A previous study also showed that elevated PVR/TIGIT expression was associated with a reduction in IFN-γ, but was not necessarily correlated with reduced CD8+ T cell infiltration in the tumor before immunotherapy." (PMID 36552960, 2022). "Based on the studies of CD155/TIGIT in tumor and immunology, it is suggested that TIGIT/CD155 is a promising target." (PMID 35433470, 2022). "TIGIT suppresses the immune system by binding to three ligands on tumour cells: CD155, CD112, and CD113." (PMID 35729552, 2022). "Smaller volumes and weights of tumors were observed on day 21 after tumor challenge in mice treated with anti-TIGIT and OX." (PMID 36389751, 2022). "We confirmed that the combined blockade of TIGIT and PD-1 further enhanced the immune response in tumour-bearing mice and suppressed tumour growth compared with targeting either checkpoint alone." (PMID 35729552, 2022).
tumor (continued). "The results showed that CTLA4, HAVCR2, PDCD1, PDCD1LG2, and TIGIT significantly differed in tumor tissues and normal tissues." (PMID 36618928, 2022). "BiPT-23 represents novel immunotherapy engineered to prevent hyperprogression of cancer with PD-1 blockade, and preferentially killed PD-L1+ tumor cells, and TIGIT+ Tregs but maintained CD11b+F4/80+ immune cells within the tumor microenvironment (TME)." (PMID 36289396, 2022). "Conversely, the anti-TIGIT treatment prevented T cells exhaustion, decreased growth rate of tumor cells, and prolonged survival of MM mice." (PMID 36605439, 2022). "CD155, one of the main ligands of TIGIT, exerts functions via different mechanisms in tumor and immunology." (PMID 35433470, 2022). "TIGIT can also mediate tumor immune escape in a bacteria-dependent manner, in which tumor cells directly interact with TIGIT to restrict NK and T cell activity using the Fap2 protein of Fusobacterium nucleatum." (PMID 35433470, 2022). "Blockade of TIGIT with a monoclonal antibody increases antitumoral effector T cells and delays tumor growth in vitro." (PMID 35971106, 2022). "In summary, our study demonstrated the immune activation and anti-tumor activity of an anti-TIGIT mAb BGB-A1217 in pre-clinical models." (PMID 35273608, 2022). "In numerous pre-clinical and clinical trials, anti-TIGIT antibody therapy has achieved significant tumor-suppressive efficacy." (PMID 35958238, 2022). "Based on this, and our observation that CD226 is readily expressed on neoantigen-specific T cells after vaccination, we treated tumor-bearing mice with combination PD-1/TIGIT blockade and neoantigen vaccine." (PMID 36569934, 2022). "In CLL, a tumor-supportive role of TIGIT+CD4+ T cells was observed in the presence of TIGIT-Fc via down-regulation of IFNγ and IL-10 production." (PMID 35656508, 2022). "The immune checkpoint molecule TIGIT plays an inhibitory role in anti-tumor immunity by inactivating immune effector cells." (PMID 36605439, 2022). "TIGIT-expressing NK cells possessed reduced effector functions and tumor-killing capabilities, as became evident by their reduced expression of cytokines such as IFNγ and tumour necrosis factor (TNF)." (PMID 35327475, 2022). "TIGIT blocked reduced tumor growth while promoting an immune infiltration enriched in effector cytokine-secreting CD8+ T cells." (PMID 35656508, 2022). "Bladder cancer patients with failing NK cells exhibited upregulation of TIM-3 and TIGIT both in the periphery and in the tumor." (PMID 35606854, 2022). "Another study confirmed that the combination of IL-15 and TIGIT blockade activated the killing effect of tumor-infiltrating NK cells." (PMID 35433470, 2022). "PD-1 and TIGIT are well-known for their role in dampening anti-tumour immunity and promoting tumour progression." (PMID 35245832, 2022). "In pre-clinical studies, anti-TIGIT mAb monotherapy was found to inhibit tumour growth and prevent metastasis." (PMID 36297474, 2022). "TIGIT negatively regulates effector T cell activity and leads to immune tolerance for tumor cell proliferation and expansion." (PMID 35971106, 2022). "Our results showed that the high-risk group with poor survival had a higher expression of T cell exhaustion markers, such as PDCD1/PD1, CTLA4, TIM3, LAG3, VSIR and TIGIT, which lead to tumor immune evasion." (PMID 36147509, 2022). "Fusobacterium nucleatum suppressed immune cells cytotoxicity and viability to protect tumor cells from being killed by immune cells through the interaction between Fap2 and TIGIT on NK cells and T cells." (PMID 35433470, 2022). "In the spleens of KPC4580P tumor bearing mice, the TIGIT+ CD4 T cells were mostly found in the antigen-experienced CD11ahiCD49dhi cell population and did not produce IFN-γ after in vitro re-stimulation." (PMID 36569934, 2022). "In vivo experiments demonstrated the effect of the TM and immunotherapy drug (anti-PD1/anti-TIGIT) combination on BC tumor growth in mice." (PMID 35154317, 2022).
tumor (continued). "We assessed the expression of TIGIT in TILs using the MC38 tumor model, and the expression of TIGIT was significantly higher in TILs, including CD4+ TILs, CD8+ TILs, and NK cells, compared with the spleen." (PMID 35320940, 2022). "Collectively, the observed changes in ALNmet T cells suggest T‐cell recognition of tumor cells, but suppressed immunity through increased expression of TIGIT and PD‐1 in effector T cells and increased frequency of activated Tregs." (PMID 34165864, 2022). "Another study reported that TIGIT-positive NK cells infiltrating mouse subcutaneous tumours or human endometrial cancers were found to co-express other inhibitory receptors, such as LAG-3 and TIM-3, and their functions were altered." (PMID 35328510, 2022). "Increasing evidence has demonstrated that TIGIT was highly expressed on tumor-infiltrating lymphocytes (TILs) in different hematological malignancies, resulting in tumor progression and poor outcomes." (PMID 36605439, 2022). "In the tumor microenvironment and peripheral blood of cancer patients, TIGIT has usually been found to be co-expressed with PD-1 on CD8+ T cells." (PMID 36231109, 2022). "At the same time, the expression levels of cytokines and immunosuppressor molecules (PD1, PD-L1, PD-L2, CTLA4, TIGIT, TIM-3, BTLA, and LAG3) were significantly higher in low-risk groups, implying more tumor immunogenicity in the low-risk group." (PMID 36217201, 2022). "Tumor cells also acquired TIGIT expression after relapse, leading to the enhanced interaction of tumor cell TIGIT with monocyte CD155/PVR." (PMID 36163179, 2022). "In mouse pre-clinical models and cancer patients, TIGIT expression on tumor-infiltrating CD8+ T cells often links with augmented expression of other inhibitory receptors like PD-1, LAG-3, TIM-3, and decreased expression of DNAM-1." (PMID 35999569, 2022). "Anti-TIGIT/CD155 pathway treatment significantly inhibited tumor growth in mouse models of transgenic head and neck squamous cell carcinoma." (PMID 35585567, 2022). "PD-1 and TIGIT signaling blockade in vivo reverses T cell dysfunction and enhances neoantigen vaccine-induced T cell responses and tumor regression." (PMID 36569934, 2022). "The combined blockade of TIGIT and PD-1 further inhibited tumour growth in C57BL/6 mice compared with the blockade of TIGIT alone." (PMID 35729552, 2022). "On the contrary, TIGIT/ligand interactions using recombinant TIGIT-Fc molecule immunostimulatory functions were shown in xenograft mouse models containing different human tumor cells (A375, A431, SK-BR-3, SK-OV-3, and H2126) co-implanted with human T cells." (PMID 35656508, 2022). "For OAS, patients with a lower intratumoral TIGIT expression in CD3+ cells showed a 5-year survival of 38.3%, whereas tumor patients with overexpression of TIGIT in CD3+ cells displayed a 5-year OAS of 55.2% (p = 0.025)." (PMID 36551992, 2022). "It has been shown that TIGIT negatively regulates cytotoxic effector cell functions and clinical trials are already testing the advantages of TIGIT blockade in different tumor entities." (PMID 35326415, 2022). "Using the xCELLigence plates, we observed that combined therapy against the IL6R/STAT-3 axis and TIGIT increased the cytotoxicity of NK cells against tumor cells." (PMID 35465350, 2022). "It has been found that TIGIT can enhance the activity of Treg cells and contribute to the formation of tumor immune suppression microenvironment." (PMID 36467413, 2022). "We investigated the ability of neoantigen vaccine alone, or in combination with PD-1 and TIGIT signaling blockade to impact tumor growth." (PMID 36569934, 2022). "Regarding immune checkpoints associated with tumor cell immune evasion, such as CTLA-4, PD-1, PD-L1, TIGIT, these inhibitory receptors/ligands suppress antitumor immune responses by altering their expression levels." (PMID 36276981, 2022).
tumor (continued). "As TIGIT expression is a sign of tumor antigen-specific cytotoxic T cells and TILs, we expect that pharmacological blockade of TIGIT results in an enhanced cytotoxic T cell-mediated immune response." (PMID 36551992, 2022). "Their antibody targeting mouse TIGIT (313R12) was shown to have positive effects on murine models of colon and kidney cancer through tumor growth inhibition." (PMID 35327475, 2022). "Curiously, in mouse tumor models, ICB with anti-TIGIT mAbs Fc variants proves that FcγR co-engagement on antigen presenting cells (APCs) increases T cell responses." (PMID 36231109, 2022). "We showed coordinated expression of TIGIT in exhausted and regulatory T cells and Nectin in tumor cells." (PMID 35995947, 2022). "Injecting the blocking antibody TIGIT in vivo inhibits tumour growth and enhances CD8+ T lymphocyte function." (PMID 35729552, 2022). "In this study, we found that low-dose oxaliplatin (OX), an immunogenic cell death (ICD)-induced drug, increased the antitumor response of TIGIT blockade against CT26 tumor, which is regarded as a MSS tumor." (PMID 36389751, 2022). "Recently, it was demonstrated that TIGIT blockade elicits NK-mediated antitumoral immunity in tumor-bearing mouse models." (PMID 35164813, 2022). "TIGIT pathway regulates T cell-mediated tumor recognition in vivo and in vitro and represents an exciting target for checkpoint blockade immunotherapy." (PMID 35656508, 2022). "TIGIT, a significant inhibitor of antitumor responses, blocks the tumor immune cycle in multiple steps." (PMID 36159861, 2022). "TIGIT expression is highly expressed on Treg cells, relative to effector T cells, and is further elevated on Tregs in tumor microenvironment." (PMID 35967421, 2022). "Upon binding to its ligand CD155 expressed by tumor cells, TIGIT-expressing NK cells dramatically diminish their cell cytotoxicity." (PMID 36189222, 2022). "The chronic inflammation induces immune exhaustion and dysfunction by firmly braking the immune activation signals via inducing expression of multiple IC molecules, including CTLA4, PD1, TIM3, LAG3, and TIGIT, in anti-tumor effector cells." (PMID 36211375, 2022). "The general perception is that IC molecules, such as PD1, CTLA4, LAG3, and TIGIT, are expressed in T cells and NK cells, and the ligands are expressed in the other cells, including tumor cells and myeloid cells." (PMID 36211375, 2022). "Preclinical research has demonstrated that blocking TIGIT alone or combined with PD-1 improves anti-tumor immune responses." (PMID 36605439, 2022). "In tumor models, TIGIT exerts its regulatory function and inhibits NK-mediated cytotoxicity on tumor cells to promote immune evasion." (PMID 36159789, 2022). "Here, FAK inhibition via VS-4718 combined with blocking TIGIT antibody immunotherapy led to immune cell activation and decreased tumour burden, enhancing mouse survival." (PMID 35929603, 2022). "To do this, we first examined the expression of TIGIT in peripheral blood and tumor specimens derived from PDAC patients." (PMID 36569934, 2022). "Reinforced by the immunohistochemical study of the in situ expression of ICs and their ligands in CRC sections, our results highlight the TIGIT/CD155 axis as the most likely to inhibit the majority of anti-tumor T responses." (PMID 36077799, 2022). "When anti-PD1 or anti-TIGIT were used simultaneously, the inhibition of tumor significantly exceeded that in the control group." (PMID 35154317, 2022). "In the present study, we found that the anti-TIGIT treatment alone exerted limited effects on tumor growth and mouse survival in the mouse model with MC38." (PMID 35320940, 2022). "It is with hope that an increased number of immune checkpoints (such as CTLA-4, PD-1, LAG-3, TIM-3, and TIGIT) be documented, although some tumor patients show immunotherapy tolerance." (PMID 35392063, 2022).
tumor (continued). "In summary, the expression of TIGIT was increased after MWA, and the addition of anti-TIGIT therapy to MWA synergistically inhibited the growth of the tumor, increased the number of effector CD8+ T cells, and reversed the function of exhausted CD8+ T cells." (PMID 35320940, 2022). "Several immune inhibitor receptors (IRs), such as TIGIT, are upregulated in solid cancers and take part in tumor immune escape." (PMID 36211383, 2022). "TIGIT is an emerging immune checkpoint expressed on tumor-infiltrating CD8+ T cells, TH, Tregs, and NK cells in various solid tumors including GC, which is associated with poor prognosis in various malignancies." (PMID 36225938, 2022). "To date, immunotherapy targeting TIGIT has shown significant anti-tumor effects in several pieces of research." (PMID 36605439, 2022). "Similar to other UV-induced tumors, PDS are inflammatory and immunogenic tumors (with a high number of CD4+/CD8+ tumor-infiltrating lymphocytes (TILs) and checkpoint molecule expression such as PD-L1, LAG-3, TIGIT) with a very high mutational burden." (PMID 36465341, 2022). "Based on the negative regulatory effect of TIGIT on tumor immunity, currently, there are a variety of anti-TIGIT mAbs as monotherapy or combined with PD-1/PD-L1 antibody or combined with chemotherapy to treat tumors." (PMID 36225938, 2022). "It has been reported that TIGIT and E. multilocularis infection in the liver can induce NK cell depletion and immune escape in tumor microenvironment based on clinical samples and mouse models." (PMID 35433470, 2022). "In preclinical studies, COM902, a monoclonal antibody targeting TIGIT, has been shown to enhance antitumor immune response and suppress tumor growth." (PMID 36140182, 2022). "Combination therapy with anti-TIGIT and OX suppressed tumor growth and significantly increased survival." (PMID 36389751, 2022). "TIGIT regulates the anticancer immune response via CD4+ Tregs which are related to tumor burden in OC patients." (PMID 36497240, 2022). "TIGIT ultimately suppresses anti-tumor immunity through binding to PVR and a subsequent series of responses." (PMID 36558902, 2022). "Binding of TIGIT to CD155 (poliovirus receptor PVR) expressed on tumor cells results in the decreased secretion of pro-inflammatory cytokines such as IFN-γ, IL-17a, and TNF-α, and an increased secretion of the anti-inflammatory cytokine IL-10." (PMID 35345849, 2022). "In the same study, while TIGIT+ T-cells were mostly PD1+ or CTLA-4+ in all tumor-bearing models, TIGIT+ NK cells were mostly both PD1– and CTLA-4–." (PMID 35008385, 2022). "Analogously, recent research indicates that TIGIT plays a tumor-promoting role in several malignant entities." (PMID 36551992, 2022). "In the described case, the Fap2 protein of F. nucleatum was shown to bind TIGIT and inactivate anti-tumor lymphocytes, providing immune evasion for the spreading cancer." (PMID 35513379, 2022). "In KPC4580P tumor bearing mice, TIGIT+ T cells were present in spleens and were enriched in the TILs, indicating a T- cell exhaustion/dysfunctional phenotype." (PMID 36569934, 2022). "Effective tumor control for certain types of cancer can be expected by combining anti-TIGIT with other ICB inhibitors." (PMID 36189222, 2022). "TIGIT is an inhibitory receptor expressed on lymphocytes that has recently attracted attention as the latest target for tumor immunotherapy." (PMID 36159861, 2022). "In various malignant entities, those Tregs present in the immune microenvironment of the tumor regularly express TIGIT on their cell surface, and it was shown that blockade of TIGIT leads to a significant decrease in Tregs." (PMID 36551992, 2022). "Aside from the PD-1 blockade, other immune checkpoints blockades (ICB) combined with TIGIT inhibition also increase anti-tumor immunity." (PMID 36231109, 2022). "More profoundly, the co-blockade of LAG3 in tandem with TIGIT affected additional tumor control, translating to a survival rate of 37.5% in mice." (PMID 36123677, 2022).